CST1 (cystatin SN)
Description:
Human saliva appears to contain several cysteine proteinase inhibitors that are immunologically related to cystatin S but that differ in their specificity due to amino acid sequence differences. Cystatin SN, with a pI of 7.5, is a much better inhibitor of papain and dipeptidyl peptidase I than is cystatin S, although both inhibit ficin equally well.
Tractability: Antibody: UniProt places it where antibodies can reach, with high confidence; UniProt predicts a signal peptide or a membrane-spanning region; its Gene Ontology location is reachable by antibodies, with medium confidence.
Gene: Protein-coding gene on chromosome 20 (23,747,562 to 23,751,268, reverse strand). Ensembl gene ENSG00000170373.
Subcellular location: Secreted
Gene Ontology:
Molecular function: protein binding; cysteine-type endopeptidase inhibitor activity
Biological process: detection of chemical stimulus involved in sensory perception of bitter taste
Cellular component: extracellular region; cytoplasm; vesicle
Genetic constraint (gnomAD): Loss-of-function variants: 21 observed, 11.75 expected, observed/expected ratio (o/e) 1.79, 90% interval 1.21 to 1.96. The synonymous counts are far from expectation, so gnomAD's model fits this gene poorly and the ratio says little. Missense variants: 247 observed, 178.51 expected, observed/expected ratio (o/e) 1.38, 90% interval 1.25 to 1.54. Synonymous variants: 95 observed, 72.43 expected, observed/expected ratio (o/e) 1.31, 90% interval 1.11 to 1.55.
Homologues: Orthologues: macaque CST2 (81% identical), zebrafish si:busm1-57f23.1 (26% identical), Caenorhabditis elegans cpi-1 (21% identical), Caenorhabditis elegans cpi-2 (19% identical), Caenorhabditis elegans K08B4.7 (9% identical). Paralogues in human: CST4 (87% identical), CST2 (86% identical), CST3 (57% identical), CST5 (55% identical), CST6 (33% identical), CST7 (28% identical), CST8 (28% identical), CSTL1 (27% identical), CST9L (26% identical), CST11 (25% identical), CST9 (21% identical).
Diseases named in the same sentence as CST1 in open-access papers:
CST1 is named in the same sentence as 68 diseases in open-access papers, as found by Europe PMC text mining. Sharing a sentence is not in itself a finding about the gene and the disease. The quoted sentences say what the papers report.
cyst (49 papers, 2015 to 2025). A sac-like closed membranous structure that may be empty or contain fluid or amorphous material. "O-linked glycosylation of CST1 is essential for establishing cyst wall thickness and cyst stability." (PMID 32132158, 2020). "Genetic deletion of CST1 reduced the number of brain cysts, and these CST1-deficient cysts exhibited a fragile-cyst phenotype characterized by a thin cyst wall and cysts that were easily disrupted by mechanical force." (PMID 32132158, 2020). "Following the induction of cyst formation, the membrane encircling these isolates was able to bind to Dolichos biflorus agglutinin, which recognizes specific glycosylation of CST1 protein associated with the cyst wall." (PMID 32012177, 2020). "If CST1 has the capability to associate with membranes and build a protein-based scaffold from the membrane, then it is likely that CST1 would associate not only with the limiting cyst membrane but also with other membranes present in the developing cyst wall." (PMID 31619500, 2019). "DBA staining of the cyst wall is principally due to O-glycosylation of the mucin-like glycoprotein CST1, since deletion of CST1, pp-GalNAcT2, or pp-GalNAcT3 led to a loss of staining by this lectin." (PMID 30773146, 2019). "As the CST1 pulldown in our approach was performed with membrane fragments and not soluble proteins, the data set we obtained revealed not only CST1-interacting proteins but also proteins that indirectly associate with CST1 through intact cyst wall structures." (PMID 31040239, 2019). "CST1 localizes throughout granular material in the cyst wall, and genetic deletion of CST1 results in the loss of this granular material, thin cyst walls, and fragile cysts." (PMID 31619500, 2019). "It has been hypothesized that the high glycosylation of the CST1 mucin domain could act as a bonding agent for other proteins associated with the cyst wall, such as dense granule proteins (GRAs)." (PMID 39189782, 2024). "However, whether or how CST1 associates with the limiting cyst membrane early after differentiation is unknown." (PMID 31619500, 2019). "O-glycosylation of the protein CST1 by the mucin-type O-glycosyltransferase T. gondii (Txg) GalNAc-T3 influences cyst wall rigidity and stability." (PMID 38710711, 2024). "Previous studies using electron microscopy have shown that CST1 is expressed in the granular material in the cyst wall under the limiting membrane." (PMID 39189782, 2024). "Some of the GRA proteins, especially those associated with the IVN network (GRA2, GRA6, GRA4, and GRA12), relocalize to the forming cyst wall and impact CST1 localization." (PMID 39189782, 2024). "This, as well as its relocation to the cyst wall with the subsequent co-localization with the major structural protein CST1, suggests that GRA2 retains its role in the organization of the parasitic structures after stage conversion." (PMID 39189782, 2024). "These mucin-like domains likely protect bradyzoites within the cyst from external environmental influences, making CST1 crucial for the survival of T. gondii." (PMID 39599575, 2024). "In contrast, in the U-ExM-expanded T. gondii cysts from D7 bradyzoite culture, a large black gap was consistently visible between the cyst, with anti-CST1 antibody used as a cyst-wall marker, and the surrounding tissue of the U-ExM-expanded host cell." (PMID 39189782, 2024). "As the cyst’s main structural protein CST1 contains a mucin domain, we added an enzymatic digestion step using the pan-mucinase StcE prior to the expansion protocol." (PMID 39189782, 2024). "The CST1 protein in the cyst wall, a glycoprotein, plays a crucial role in stabilizing the cyst wall and shielding it from host immune responses." (PMID 39599575, 2024). "Using StcE-enhanced U-ExM, we clarified the localization of the GRA2 protein, which is important for establishing a normal cyst, observing GRA2 granules spanning across the CST1 cyst wall." (PMID 39189782, 2024).
cyst (continued). "We therefore used the StcE–U-ExM protocol to clarify the location of GRA2 relative to CST1 protein in the T. gondii cyst wall in HFFs (D7) and primary rat neuronal cultures (D14)." (PMID 39189782, 2024). "The composition of the T. gondii cyst wall is complex, primarily consisting of CST1 and dense granule proteins (GRAs)." (PMID 39599575, 2024). "Previously published studies based on standard confocal images show full co-localization of GRA2 and CST1, both appearing as a smooth signal across the cyst wall." (PMID 39189782, 2024). "We then verified the substrate preference of TxgGalNAc-T3 for endogenous T. gondii cyst wall proteins using peptides and glycopeptides from CST1 and SRS13." (PMID 38710711, 2024). "In our study, we also investigated the changes in the transcription levels of some important genes related to cysts, including cst1, a cyst wall protein essential for maintaining cyst integrity." (PMID 39080770, 2024). "StcE cuts through the mucin domains of the major structural protein of the cyst wall CST1, allowing the cyst to expand fully while preserving the CST1 signal in immunofluorescence assays." (PMID 39189782, 2024). "We then used the technique to clarify the location of the GRA2 protein relative to the CST1-positive layer in the cyst wall." (PMID 39189782, 2024). "Of these, CST1 is a major structural component of the cyst and is a SAG1-related sequence protein with a heavily glycosylated mucin domain." (PMID 39189782, 2024). "From a biological perspective, CST1, which contains a mucin-like domain and is O-GalNAc-glycosylated, resembles the cyst wall protein SRS13 from the SRS protein family." (PMID 39599575, 2024). "To accommodate this limitation, we focused on using the cyst persistence factor CST1 and assessed the feasibility of enhanced cyst reduction since most of the T. gondii vaccine studies reported to date emphasized the use of host invasion factors as antigens." (PMID 37104285, 2023). "T. gondii cyst wall protein (CST1) as a cyst persistence factor is critical for cyst wall integrity and bradyzoite persistence." (PMID 37104285, 2023). "Fluorescence was detected from the entirety of the cyst surface, thus confirming that the antibody used in the study was capable of detecting the CST1 antigen that lines the cyst walls." (PMID 37104285, 2023). "Using FITC-conjugated secondary antibodies, CST1 VLP immune sera interaction with the cyst wall was confirmed." (PMID 37104285, 2023). "Several proteins have been identified in the TC wall, including a 65KDa protein abundant in its matrix, the CST1 protein, which is associated to the integrity of in vivo produced TC, and BCP1, which is also essential to cyst wall formation." (PMID 36311681, 2022). "Like CST1, another glycoprotein proteophosphoglycan (TgPPG1) is upregulated in bradyzoites and enhances cyst wall formation." (PMID 36439853, 2022). "The cyst wall contains several prominent glycoproteins, including the major cyst wall glycoprotein CST1 (a 116 kDa glycoprotein)." (PMID 36566237, 2022). "The cyst wall is enriched in dense granule proteins, stage-specific glycoproteins such as CST1, and partially characterized carbohydrates." (PMID 34860156, 2021). "T. gondii cyst wall CST1 formation around bradyzoites in IMR-32 cells was found only in IFN-γ-stimulated cells." (PMID 35096641, 2021). "SRS44, also known as CST1, is a cyst wall component that is expressed above the 89th percentile in both bradyzoite stages and maintains the integrity of the cyst during chronic infection." (PMID 33816350, 2021). "T. gondii bradyzoite antigen 1 (BAG1) is a bradyzoite-specific marker, and cyst wall markers [e.g., bradyzoite-specific cyst-wall protein 1 (CST1)], which are markers of bradyzoite differentiation, have also been identified." (PMID 35096641, 2021).
cyst (continued). "Genetic deletion of CST1 results in a leaky-cyst phenotype marked by the escape of cyst matrix proteins from the cyst, which supports the previously proposed model that O-linked N-acetylgalactosamine glycosylation regulates the permeability of the cyst wall." (PMID 32132158, 2020). "To confirm that CST1 and s-WGA were colocalized in the cyst wall, we measured the cyst fluorescence intensity profiles for CST1 and s-WGA." (PMID 32132158, 2020). "While CST1 was preferentially localized to the cyst wall (cyst periphery/cyst interior ratio of >1.0), the N-acetylglucosamine-modified molecules that bind s-WGA were present in the cyst wall and in the cyst matrix (cyst periphery/cyst interior ratio of <1.0)." (PMID 32132158, 2020). "Under bradyzoite induction conditions, the BirA*-tagged TgME49_258870, TgME49_204340, and TgME49_310790 proteins localized to the cyst wall as demonstrated by their colocalization with CST1 (right)." (PMID 32019789, 2020). "While CST1 has traditionally been thought to be specific to the slow-growing bradyzoite stage of Toxoplasma, due to its detection in the cyst wall, our results, along with those of others, provide clear evidence for CST1 protein expression in tachyzoites." (PMID 32075880, 2020). "The use of the CST1 monoclonal antibody to purify fragments of the cyst wall and identify the purified components has been successful at identifying many cyst constituents." (PMID 32374791, 2020). "As expected, CST1 localized to the cyst wall, while s-WGA localized to the cyst periphery/wall as well as to the cyst matrix in immature 3-day-old cysts and in mature 7- and 10-day-old cysts." (PMID 32132158, 2020). "To investigate the localization of s-WGA in relation to the major cyst wall protein CST1, we differentiated cysts for 3, 7, or 10 days and determined the localizations of s-WGA and CST1." (PMID 32132158, 2020). "The cyst wall material is heavily glycosylated, and glycoproteins such as PPG1 or CST1 are important for the formation of the cyst wall structure." (PMID 32245165, 2020). "Our results show that the cyst wall-glycosylated molecule(s) that binds s-WGA colocalized with CST1 in the cyst wall." (PMID 32132158, 2020). "s-WGA colocalized with GRA4 and GRA6 in the cyst matrix and with GRA4, GRA6, and CST1 in the cyst wall." (PMID 32132158, 2020). "We first confirmed an occurrence of perforin-dependent cyst removal by measuring expression levels of mRNA for bradyzoite (cyst)-specific molecules CST1 and LDH2 in the brains of the recipient animals by real-time RT-PCR." (PMID 32291349, 2020). "The fluorescence intensity peak of s-WGA overlapped that of CST1, the major cyst wall glycoprotein that is localized throughout the cyst wall." (PMID 32132158, 2020). "The relative accumulation of GRA4, GRA6, and CST1 at the cyst periphery/wall was delayed in Δgra2 cysts." (PMID 32132158, 2020). "The purification of the cyst wall using Percoll gradient followed by immunoprecipitation with an anti-CST1 monoclonal antibody was used to identify cyst components." (PMID 32374791, 2020). "MYR1 was detected in the nascent cyst wall of vacuoles undergoing differentiation as early as 1 day p.i. and up to 7 days p.i., as determined by colocalization with glycosylated CST1, an early marker of bradyzoite differentiation." (PMID 32156805, 2020). "While CST1 is a crucial component of the cyst wall, parasites with CST1 deleted (ΔCST1 strains) are still able to form cysts, albeit smaller and more fragile ones." (PMID 32075884, 2020). "CST1 was present in all layers of the cyst wall and colocalized with s-WGA in 3-day-old, 7-day-old, and 10-day-old cysts." (PMID 32132158, 2020). "The deletion of the glycoprotein CST1 results in fragile cysts with thin cyst walls and lower cyst burden in a chronic-infection model." (PMID 32374791, 2020). "Our data suggest DBA stain, like CST1, is present throughout the cyst wall compartment early after differentiation and during cyst maturation." (PMID 31619500, 2019).
cyst (continued). "Our data showed that PruΔgra12 parasites exhibited a relative delay in the accumulation of the CST1 major cyst wall protein at the cyst periphery, but this defect was mild in comparison to the severe defects previously reported in PruΔasp5 cysts." (PMID 31266861, 2019). "This pattern continued to day 3, which was the first time when the relative accumulation of the GRA proteins at the periphery fell below the CST1 DBA stain ratio (cyst periphery/cyst interior)." (PMID 31619500, 2019). "CST1 is the selective binding target of the cyst wall-specific Dolichos biflorus agglutinin (DBA) stain." (PMID 31619500, 2019). "GRA9 and GRA1 were colocalized and were more concentrated at the cyst periphery than CST1-stained DBA." (PMID 31619500, 2019). "These validation data on the hypothetical proteins identified by the Percoll fractionation followed by CST1 immunoprecipitation confirmed that this technique was able to enrich cyst wall fragments for proteomic analysis." (PMID 31040239, 2019). "During the first 7 days of cyst development, the cyst periphery/cyst interior ratio of DBA staining of the major cyst wall protein CST1 was remarkably consistent, ranging between 1.02 and 1.26." (PMID 31619500, 2019). "In order to understand the composition of the cyst wall, a proteomic analysis of purified cyst wall fragments, that were enriched with Percoll gradients and subsequently immunoprecipitated with CST1 antibody, was performed." (PMID 31040239, 2019). "The cyst wall contains several prominent glycoproteins, including the major cyst wall glycoprotein CST1." (PMID 31619500, 2019). "CST1 confers structural rigidity to the cyst wall, and the O-GalNAc modification is required for this function." (PMID 30773146, 2019). "CST1 is a glycoprotein found within the cyst wall and is responsible for Dolichos biflorus binding to T. gondii cysts." (PMID 30333181, 2018). "Deletion of CST1 results in a thin and fragile cyst wall, as well as reduced cyst numbers in the brains of infected mice." (PMID 30333181, 2018). "The exact molecular mechanism(s) of how CST1 and its posttranslational glycosylation result in structural integrity of the cyst wall and the assembly of this structure remain to be elucidated." (PMID 28074022, 2017). "Previously, we demonstrated that a mucin-like glycoprotein, CST1, localizes to the cyst wall and confers structural rigidity on brain cysts in a mucin-like domain-dependent manner." (PMID 28074022, 2017). "We previously demonstrated that cyst wall glycoprotein CST1 has a large mucin-like domain that is modified with O-GalNAc glycans." (PMID 28074022, 2017). "Previously, our group demonstrated that the mucin-like glycoprotein CST1 forms the cyst wall layer and confers cyst wall structural rigidity as well as facilitating persistence of cysts in mouse brain during chronic infection." (PMID 28074022, 2017). "The mucin domain of CST1 is, therefore, a critical component of the cyst wall that is involved in essential functions of this structure." (PMID 28074022, 2017). "Our initial observation of the CST1 role in cyst wall structural rigidity demonstrated using deletion mutants of CST1 domains that the mucin-like domain of CST1 is necessary for the in vivo phenotype." (PMID 28074022, 2017). "Both T2 and T3 glycosylate the CST1 mucin-like domain, and this glycosylation is necessary for CST1 to confer structural rigidity on the cyst wall." (PMID 28074022, 2017). "The RHΔku80Δpkac3 strain demonstrated cyst wall staining under normal culture conditions (~14% in RHΔku80Δpkac3), whereas the parental strain had few CST1-positive vacuoles (~1% in parental RHΔku80Δhxgprt)." (PMID 27247232, 2016). "Importantly, CST1 expression during the cyst stage is specific, reducing cross-reactivity with other antigens and enhancing the specificity of CST1 as a marker for chronic T. gondii infection." (PMID 39599575, 2024).